LINC01269 (long independently transcribed non-coding RNA 1269)
Synonyms: HNSCAT1; PARLncRNA-1; lncRNA-RP6-65G23.1
Gene: Long non-coding RNA gene on chromosome 14 (70,697,948 to 70,714,886, forward strand). Ensembl gene ENSG00000258689.
Diseases named in the same sentence as LINC01269 in open-access papers:
LINC01269 is named in the same sentence as 6 diseases in open-access papers, as found by Europe PMC text mining. Sharing a sentence is not in itself a finding about the gene and the disease. The quoted sentences say what the papers report.
esophageal carcinoma (1 paper, 2022). A primary or metastatic malignant neoplasm involving the esophagus. "Through pancancer analysis, we further confirmed that linc01269 was remarkably downregulated in HNSC and esophageal carcinoma (ESCA), while other malignancies remained unchanged." (PMID 35965679, 2022).
gastric cancer (1 paper, 2022). A primary or metastatic malignant neoplasm involving the stomach. "In addition, LINC01269 is related to the prognosis of liver cancer, while GACAT2 influences the prognosis of gastric cancer." (PMID 36118853, 2022).
tumor (1 paper, 2022). "In this study, we identified a novel cytoplasmic transcript, HNSC-associated transcript 1 (HNSCAT1, previously recognized as linc01269), that was downregulated in tumor samples and was also associated with favorable outcomes in HNSC." (PMID 35965679, 2022).
LINC01269 also shares sentences with these, for which no sentence is quoted: acute myocardial infarction (1 paper); head and neck squamous cell carcinoma (1); liver cancer (1).